VAV1 (vav guanine nucleotide exchange factor 1)
Diseases named in the same sentence as VAV1 in open-access papers (continued):
Sharing a sentence is not in itself a finding about the gene and the disease.
cancer (continued). "Meanwhile, there is evidence that Lyn regulation of VAV1 in cancers activates the Rac1-PAK1 kinase cascade to stabilize Slug and Snail, allowing them to initiate transcription of EMT genes 14, so the metastasis-related tyrosine protein kinase LYN attracted our attention." (PMID 35414768, 2022). "In addition, numerous studies have reported the unexpected expression of Vav1, normally found only in the hematopoietic system, in a variety of human cancers, such as neuroblastoma, lung, breast, ovarian, prostate, esophageal, and brain tumors." (PMID 32277014, 2020). "Consistent with this, AATK protein expression significantly associates with nuclear VAV1 localization in PDA patients, in which AATK-negative cases were overrepresented with cytosolic VAV1 localization, epithelial-to-mesenchymal transition, and dissemination of cancer cells." (PMID 32552862, 2020). "The importance of Vav1 in cancer is mainly due to its function as a GEF for Rho/Rac GTPases." (PMID 30297765, 2018). "Our results thus categorically demonstrate the need for analysis of each of the Vav1 mutations detected in human cancers, since not all Vav1 mutants have transforming properties, as demonstrated here with respect to L801P." (PMID 30297765, 2018). "Our study strongly supports the classification of Vav1 as a bona fide oncogene in human cancer." (PMID 30297765, 2018). "Thus, the accumulating data clearly point to an important role of ectopically expressed wild-type Vav1 in human cancer." (PMID 26353933, 2015). "While it is now clear that Vav1 expression is deregulated in some cancers, leading to expression outside the hematopoietic system, it also emerges now as a mutated gene in human cancers of various origins; however, the activity and contribution of the various mutations is still unclear." (PMID 26353933, 2015). "Since Rho GTPases were reported to control cytoskeleton organization and cellular activities, such as the JNK (c-Jun N-terminal kinase) and p38 MAPK (mitogen-activated protein kinase) cascades, it is conceivable that Vav1 also controls these pathways in cancer." (PMID 26353933, 2015). "Our recent data suggest that Vav1 may also contribute to cancers by regulating growth factor expression." (PMID 26353933, 2015). "This recurring theme suggests that Vav1 might contribute to the progression of cancer by regulating secretion of autocrine ligands critical for tumorigenicity, as well as affecting the expression of other proteins critical for various cellular functions." (PMID 26353933, 2015). "The biological importance of the Vav1 mutants identified in human cancer needs further exploration, including testing the role of the various mutants in cognate tissues, assessing GEF activity of mutants, and testing their ability to associate with other proteins." (PMID 26353933, 2015). "Indeed, Vav1 regulates cytoskeleton reorganization in response to extracellular stimuli and participates in cancer cell invasion." (PMID 25313137, 2014). "Thus, potentially, Vav1 can be tyrosine phosphorylated in cancer cells through numerous tyrosine kinase growth factor receptors (RTKs), partly not analyzed yet." (PMID 25313137, 2014). "Thus far, the main role attributed to Vav1 in cancer was its regulation of the activity of Rho/Rac GTPases." (PMID 25313137, 2014). "One signal transducer that has been shown to be deregulated in several human cancers is Vav1." (PMID 25313137, 2014). "The anti-apoptotic effect of Vav1 has been shown in cancers of hematopoietic origin." (PMID 23342133, 2013). "In addition, numerous studies have reported the unexpected expression of Vav1 in a variety of human cancers of various histological origin including the hematopoietic system, as well as solid tumors such as neuroblastoma, lung, pancreas, breast, ovarian, prostate, esophageal, and brain tumors." (PMID 35326399, 2022).
cancer (continued). "Therefore, Vav1 may play opposing roles depending on the type of cancer, and further studies are needed to determine and differentiate the signaling axis by which Vav1 is expressed and activated in malignant tumors." (PMID 32322580, 2020). "Therefore, it remains to be tested whether the cancer-identified Vav1 mutants are transforimg in such experimental conditions." (PMID 26353933, 2015). "However, the activity and contribution to cancer of these Vav1 mutants is still unclear." (PMID 26353933, 2015). "This recurring theme suggests that Vav1 might contribute to the progression of cancer by regulating secretion of autocrine ligands critical for tumorigenicity, as well as affecting the expression of other proteins critical for various functions in the cell, as noted by us herein for the first time." (PMID 25313137, 2014). "Vav1 mutations have not been detected so far in human cancer." (PMID 22253833, 2012). "Since T cells play a crucial role in maintaining immune system homeostasis, the Themis/Vav1 signaling hub could thus represent a checkpoint for T cell functions and play an important role in controlling immune responses against self-antigens, cancer, and infectious diseases." (PMID 38565808, 2024). "As EGF receptor, Vav1, RhoA, Rac1, and BPGAP1 are all associated with oncogenesis and/or cancer metastasis, the identification of this novel EGFR-BPGAP1-Vav1-Rac1-RhoA signaling axis could provide new approaches to a combinatorial therapeutic intervention in cancer progression." (PMID 36598812, 2023). "Taken together, our results suggest that abnormal expression of wild-type Vav1 in certain histological compartment leads to changes in signal transduction pathways as well as in growth factor/cytokine expression, which might contribute to development of cancer in adjacent histological compartments." (PMID 35326399, 2022). "The potential link between Vav1 activity in ERK phosphorylation was noted in hematopoietic cells, where Vav1 is physiologically active, as well as in cancer cells." (PMID 35326399, 2022). "The result demonstrated a significant value of VAV1, RHOA, and ZC3HAV1 in predicting the therapeutic efficacy of ICIs for patients with various cancer types." (PMID 36224658, 2022). "BCL9 suppression blocks VAV1 phosphorylation in CD8+ T cell as well as increases GLI1 and PATCH expression to promote CD155 expression in cancer cells." (PMID 34417435, 2021). "BCL9 suppression induces phosphorylation of VAV1 in CD8+ T cells and increases GLI1 and PATCH expression to promote CD155 expression in cancer cells." (PMID 34417435, 2021). "Our results showed that the heat diffusion algorithm predicted 5 putative cancer gene CDH10, CHST11, GRM3, VAV1 and CCR4 from Tier 2 of the Cancer Gene Census6." (PMID 31500564, 2019). "Clathrin, caveolin, Rabs (Rab4, Rab5A, Rab1A, Rab2A) as well as their effectors (Rab25, Vav1, Rab coupling protein,cdc42, VSP39), can contribute to the processes of cancer cell survival and metastasis, and cancer stem cell emergence." (PMID 29409507, 2018). "Our results suggest a potential cross-talk between cancer cells and the microenvironment controlled by CSF1/Vav1 signaling pathways." (PMID 26353933, 2015). "Additional results presented herein suggest a potential cross-talk between cancer cells and the microenvironment controlled by CSF1/Vav1 signaling pathways." (PMID 25313137, 2014). "Genes involved in signal transduction, an important type of pathways in cancer development, such as MARK14, VAV1 and PIK3R1 were also identified as gene signatures in this study." (PMID 21483478, 2011). "The methylation status of the VAV1 promoter is a possible mechanism contributing to the ectopic expression of VAV1 in cancers of non-hematopoietic origin." (PMID 37174676, 2023).
cancer (continued). "BPGAP1 recruits the RacGEF Vav1 under epidermal growth factor (EGF) stimulation and activates Rac1, leading to polarized cell motility, spreading, invadopodium formation, and cell extravasation and promotes cancer cell migration." (PMID 36598812, 2023). "Vav1 can be activated by various receptors in human cancers when it is overexpressed in non-hematopoietic cells, leading to signaling cascades similar to those it regulates in hematopoietic cells, including cytoskeletal reorganization and transcription." (PMID 35326399, 2022). "Key roles of CD155-CD226 and CD155-CD96 checkpoints in cancer cell/CD8+ T cell interactionPhosphorylation of VAV1 in CD8+ T cells via BCL9 suppression, mediating Wnt transcriptionUpregulation of GLI1 and PATCH expression in promoting CD155 expression in cancer cells." (PMID 36032085, 2022). "In human lymphocytes, Vav1’s promoter is unmethylated, but it is methylated to various degrees in cancers of non-hematopoietic tissues, that do not normally express Vav1." (PMID 35326399, 2022). "The fact that the mere expression of Vav1 in epithelial cells does not lead to the development of carcinomas further substantiates our previous studies with Vav1-pancreatic transgenic mice." (PMID 35326399, 2022). "Contrary to this scenario, different cancer studies have reported unexpected expression of VAV1 in tissues where it is not normally expressed, such as pancreas and lung cancer." (PMID 34571765, 2021). "While Vav1 was first identified as an oncogene capable of inducing transformation in NIH3T3 fibroblasts, accumulating results from the past decade clearly indicate its participation in human cancer through ectopic overexpression." (PMID 26353933, 2015). "Activation of Vav1 also stimulates MAPK signaling cascades, which may contribute to cancer by enhancing cell mitogenic properties." (PMID 26353933, 2015). "One mechanism suggested to play a role in ectopic expression of Vav1 in cancer of non-hematopoietic origin is the methylation status of the Vav1 promoter." (PMID 26353933, 2015). "Taken together, our results suggest that Vav1 may propagate a putative autocrine feed forward loop by upregulating expression of CSF1, which in turn induces Vav1 tyrosine phosphorylation in cancer cells." (PMID 25313137, 2014). "We demonstrate here for the first time that Vav1 can influence apoptosis in non-hematopoietic cancer cells." (PMID 23342133, 2013). "Our results provide the first evidence for regulation of Vav1 expression by Cbl-c in non-hematopoietic cells, and specifically, in cancer cells." (PMID 23342133, 2013). "However, there are no reports supporting this classification of VAV1 in solid tumors of epithelial origin or other cancers." (PMID 37174676, 2023). "Unlike the case of VAV1, there are no consistent examples of mutations for the VAV3 gene in cancer." (PMID 34571765, 2021). "This evidence suggests that the downregulation of the VAV1–CBL-B axis may not be relevant in other cancer types beyond T-ALL." (PMID 34571765, 2021). "It therefore remained to be tested whether or not the mutants in Vav1 that were identified in human cancers function as transforming genes under experimental conditions." (PMID 30297765, 2018). "The ectopic expression of Vav1 is observed in numerous non-hematopoietic cancer cells." (PMID 25426554, 2015). "Whether Vav1 can play a dual role as a pro- or an anti-apoptotic protein in cancer cells of non-hematopoietic origin has never been tested directly, yet several studies point to such roles in hematopoietic cells." (PMID 23342133, 2013). "However, there are no reports of Vav1 stimulation by CSF1 in cancer cells." (PMID 25313137, 2014). "Thus, it is conceivable that in non-hematopoietic cancer cells wild-type Vav1 might function in a similar fashion to oncogenic Vav1 in hematopoietic cells due to its constitutive activation by various aberrantly functional signaling cascades." (PMID 23342133, 2013).
cancer (continued). "Conversely, cancer cells in those mice with low or negative AATK expression, cytosolic VAV1 localization was enriched." (PMID 32552862, 2020). "Among the genes that were down-regulated in the absence of Vav1 was CSF1, as well as several genes whose products might participate in signaling events, including lysyl oxidase (LOX), known to participate in cancer development." (PMID 25313137, 2014).
infection (8 papers, 2011 to 2025). The state of being infected such as from the introduction of a foreign agent such as serum, vaccine, antigenic substance or organism. "Yet surprisingly, neutrophil recruitment is largely normal in Vav1–/– mice in various inflammation and infection models, even when Vav1-deficiency is combined with deficiencies in other Vav GEFs." (PMID 37383235, 2023). "Finally, we utilised Vav1/2-/- knockout fibroblasts for infection and gentamicin protection assays." (PMID 22204307, 2011). "Vav1 expression is reported to be restricted mainly to leukocytes, and monocytes/macrophages are an important target for DENV-infection and host inflammatory responses." (PMID 38054722, 2024). "GSEA at 24 h indicated that genes involved in infection, TLR, chemokine and cytokine signaling are enriched as before, but genes involved in phagocytosis are also enriched, including Vav1, Sirpa, Cdc42se1, Cdc42ep2, Fcgr2b/3, and Coro1a." (PMID 25888408, 2015). "The importance of Vav2 was then confirmed by the expression of dominant-negative constructs and the use of Vav1/2 knockout cells in infection assays." (PMID 22204307, 2011). "Vav1 and 2 mRNA and protein and Vav3 mRNA were present in MDMs but were not affected by DENV-infection." (PMID 38054722, 2024).
hematopoietic cancers (3 papers, 2014 to 2022). "Given that hSTAT5BN642H was found in different hematopoietic cancers, we expressed hSTAT5B or hSTAT5BN642H in mice during early hematopoiesis using the Vav1 oncogene promoter." (PMID 29200404, 2018).
Hematological Malignancies (2 papers, 2016 to 2023). "The first reports about rearrangements/mutations in VAV1 in hematologic malignancies appeared in the last decade." (PMID 37174676, 2023). "VAV1 overexpression in hematopoietic malignancies—VAV1 has also been shown to be deregulated in hematologic malignancies." (PMID 37174676, 2023). "At the pathological level, a number of features of the hematopoietic disease in VAV1-Cre-induced CBL/CBL-B DKO mice resemble those seen in JMML, as well as in previous models with CBL/CBL-B deletion or CBL RF mutation." (PMID 27449297, 2016).
inflammation (2 papers, 2012 to 2021). Aberrant reaction of the microcirculation characterized by movement of fluid and leukocytes from the blood into extravascular tissues. "That inflammation, immune system activation and imbalance, and cell proliferation and adhesion migration were mainly affected by HLA-DRA, SYK, CTLA4, VAV1, NRAS, and JAK3 signaling pathways was suggested to be the potential molecular mechanism for pulmonary inflammation and fibrosis in ACO." (PMID 33869177, 2021). "Vav1-Cre x TβRIIfx/fx mice, lacking TβRII function in hematopoietic cells, exhibited uncontrolled pulmonary inflammation and developed a lethal autoimmune syndrome at young age." (PMID 22703233, 2012).
vasculopathy (1 paper, 2019). "Transgenic expression of a mutant hSTING cDNA under the control of the Vav1 gene promoter leads to a vasculopathy similar to that of the interferonopathy, STING-associated vasculopathy of infancy." (PMID 31221625, 2019).
VAV1 also shares sentences with these, for which no sentence is quoted: adult T cell leukemia (2 papers); cervical cancer (2); esophageal squamous cell carcinoma (2); Splenomegaly (2); adenocarcinoma (1); artery thrombosis (1); B cell deficiency (1); basophilic leukemia (1); Candidemia (1); cardiovascular disease (1); chronic myelomonocytic leukemia (1); colitis (1); colorectal cancer (1); Crohn disease (1); cutaneous T-cell lymphomas (1); diabetes (1); esophageal carcinomas (1); essential thrombocythemia (1); fungal infections (1); gastric tumors (1); Hypertension (1); infectious disease (1); influenza infection (1); leishmaniasis (1); leukopenia (1); liver disease (1); lupus nephritis (1); lymphoid tumors (1); mastitis (1); metastatic disease (1).
A further 12 diseases each share a sentence with VAV1 in 1 paper.